RNU6-1337P (RNA, U6 small nuclear 1337, pseudogene)
Gene: Small nuclear RNA gene on chromosome 19 (58,483,749 to 58,483,843, reverse strand). Ensembl gene ENSG00000252334.
Homologues: Orthologues: chimpanzee U6 (99% identical), guinea pig U6 (69% identical). Paralogues in human: RNU6-1060P (83% identical), RNU6-125P (83% identical), RNU6-19P (83% identical), RNU6-540P (83% identical), RNU6-748P (83% identical), RNU6-843P (83% identical), RNU6-949P (83% identical), RNU6-1131P (82% identical), RNU6-1270P (82% identical), RNU6-15P (82% identical), RNU6-429P (82% identical), RNU6-637P (82% identical), and 1282 more.